RIC3 (RIC3 acetylcholine receptor chaperone)
Description:
Molecular chaperone which facilitates proper subunit assembly and surface trafficking of alpha-7 (CHRNA7) and alpha-8 (CHRNA8) nicotinic acetylcholine receptors. May also promote functional expression of homomeric serotoninergic 5-HT3 receptors, and of heteromeric acetylcholine receptors alpha-3/beta-2, alpha-3/beta-4, alpha-4/beta-2 and alpha-4/beta-4.
Synonyms: FLJ11608; PRO1385; AYST720; RIC-3
Tractability: Antibody: UniProt predicts a signal peptide or a membrane-spanning region. PROTAC: UniProt records ubiquitination sites on it; ubiquitination databases record sites on it.
Gene: Protein-coding gene on chromosome 11 (8,106,056 to 8,169,055, reverse strand). Ensembl gene ENSG00000166405.
Subcellular location: Endoplasmic reticulum membrane (Isoform 1); Endoplasmic reticulum membrane (Isoform 2); Golgi apparatus membrane
Gene Ontology:
Molecular function: acetylcholine receptor binding; protein folding chaperone
Biological process: positive regulation of protein localization to cell surface; protein localization to cell surface; synaptic transmission, cholinergic; protein folding
Cellular component: neuron projection; neuronal cell body; endoplasmic reticulum; endoplasmic reticulum membrane; Golgi membrane; membrane; synapse
Genetic constraint (gnomAD): Loss-of-function variants: 21 observed, 24.84 expected, observed/expected ratio (o/e) 0.85, 90% interval 0.6 to 1.22. The upper end of that interval is the gene's LOEUF score, 1.22, which puts it in group 5 of 6, group 1 being the genes least tolerant of losing a copy. Missense variants: 491 observed, 456.6 expected, observed/expected ratio (o/e) 1.08, 90% interval 1 to 1.16. Synonymous variants: 181 observed, 164.64 expected, observed/expected ratio (o/e) 1.1, 90% interval 0.97 to 1.24.
Homologues: Orthologues: chimpanzee RIC3 (99% identical), macaque RIC3 (96% identical), dog RIC3 (89% identical), rat Ric3 (87% identical), guinea pig RIC3 (86% identical), mouse Ric3 (86% identical), rabbit RIC3 (83% identical), pig RIC3 (74% identical), tropical clawed frog ric3 (53% identical), zebrafish ric3a (31% identical), Caenorhabditis elegans ric-3 (20% identical).
Diseases named in the same sentence as RIC3 in open-access papers:
RIC3 is named in the same sentence as 14 diseases in open-access papers, as found by Europe PMC text mining. Sharing a sentence is not in itself a finding about the gene and the disease. The quoted sentences say what the papers report.
Alzheimer disease (2 papers, 2016 to 2021). A progressive, neurodegenerative disease characterized by loss of function and death of nerve cells in several areas of the brain leading to loss of cognitive function such as memory and language. "In this review, we also provide evidence implicating α7 nAChRs and RIC-3 in neurodegenerative diseases such as Alzheimer’s disease (AD) and Parkinson’s disease (PD) involving neuroinflammation." (PMID 34684720, 2021).
Parkinson disease (2 papers, 2016 to 2021). A progressive degenerative disorder of the central nervous system characterized by loss of dopamine producing neurons in the substantia nigra and the presence of Lewy bodies in the substantia nigra and locus coeruleus. "Recently, the c.169C>A mutation in RIC3 (resistance to inhibitors of cholinesterase 3, MIM*610509) was found to segregate with a variable onset (30–68 years) Parkinsonism in a large family from South India." (PMID 34630269, 2021).
schizophrenia (2 papers, 2016 to 2024). A major psychotic disorder characterized by abnormalities in the perception or expression of reality. "RIC3 expression is specifically upregulated in both patients with schizophrenia and bipolar disorder, both of which include language dysfunction." (PMID 38472514, 2024). "Although the role of RIC3 in α7-signaling dysfunction has not been explored, α7 nAChR expression is reduced in the brain of schizophrenic patients and the levels of RIC3 mRNA in the brains of schizophrenia patients, postmortem, are greater than in typical brains." (PMID 38472514, 2024).
experimental autoimmune encephalomyelitis (1 paper, 2021). An autoimmune demyelinating disease of the central nervous system that is produced experimentally in animals by the injection of homogenized brain or spinal cord in Freund's adjuvant. "Further, we also describe evidence implicating this receptor and its chaperone RIC-3 in diseases of the central nervous system and in neuroinflammation, focusing on multiple sclerosis (MS) and its animal model, experimental autoimmune encephalomyelitis (EAE)." (PMID 34684720, 2021).
multiple sclerosis (1 paper, 2021). A progressive autoimmune disorder affecting the central nervous system resulting in demyelination. "Genome wide association studies (GWAS) identified polymorphisms in the ric3 region in association with multiple sclerosis (MS)." (PMID 34684720, 2021).
neuroblastoma (1 paper, 2017). Neuroblastoma (NB) is the most common solid, extracranial childhood tumor. "This method is based on the transient co-transfection of mouse neuroblastoma cells (Neuro2a) with genetic material of the mutants, in combination with a chaperone Ric-3 or NACHO and a genetically-encoded single-wavelength calcium sensor Case12." (PMID 28797116, 2017). "To achieve reliable expression of α7 nAChR and its mutants, we performed a transient co-transfection of mouse neuroblastoma cells (Neuro2a) with the plasmids coding for α7 nAChR and one of the chaperones Ric-3 or NACHO." (PMID 28797116, 2017).
tumor (6 papers, 2011 to 2021). "In another study, RIC3‐TCRBC2 fusion was identified by RNA‐Seq in T‐cell lymphoblastic lymphoma, which might be a strong driver for neoplasia‐associated mutations." (PMID 34056873, 2021). "Among the new transcript fusions that not encode chimeric proteins we identified the fusion of RIC3 to TCRBC2 gene in tumour." (PMID 30914738, 2019). "Five fusions found exclusively in tumour samples could be considered pathogenic (NFYG-TAL1, RIC3-TCRBC2, SLC35A3-HIAT1, PICALM MLLT10 and MLLT10-PICALM)." (PMID 30914738, 2019). "Using α-bungarotoxin (α-bgtx), we isolated and compared α7-nAChR-associated proteins from two stably transfected, human tumor-derived cell lines: SH-EP1-hα7 expressing human α7-nAChRs and the same cell line further transfected to express Ric-3, SH-EP1-hα7-Ric-3." (PMID 26258666, 2015). "Respectively, the expression of CDO1, CELF2, ITPRIPL1, KCNH8, RIC3, USP44 and ZSCAN23 was significantly lower in tumor tissues, whereas the expression of PTK6 and RAB25 was significantly higher in tumor tissues." (PMID 34056873, 2021). "The parental, human tumor-derived SH-EP1 epithelial cell line expresses little, if any, α7-nAChRs or Ric-3." (PMID 26258666, 2015).
cancer (3 papers, 2011 to 2021). A tumor composed of atypical neoplastic, often pleomorphic cells that invade other tissues. "Interestingly, RIC3 encodes a member of a protein family that has never been associated to cancer." (PMID 30914738, 2019). "No study has yet focused on the relationships of RIC3 and any other cancer." (PMID 34056873, 2021).
neurodegenerative disease (1 paper, 2021). A disorder of the central nervous system characterized by gradual and progressive loss of neural tissue and neurologic function. "Deregulated neuroinflammation due to dysfunction of α7 nAChR provides one explanation for involvement of this receptor and of RIC-3 in neurodegenerative diseases." (PMID 34684720, 2021). "Below we will provide evidence implicating the cholinergic anti-inflammatory pathway, α7 nAChR and RIC-3 in three neurodegenerative diseases: MS, AD and PD." (PMID 34684720, 2021).
RIC3 also shares sentences with these, for which no sentence is quoted: acute lymphoblastic T-cell leukaemia (1 paper); bipolar disorder (1); diseases of the central nervous system (1); inflammatory bowel disease (1); Obesity (1).